LETM2 (leucine zipper and EF-hand containing transmembrane protein 2)
Synonyms: FLJ25409; SLC55A2
Tractability: Antibody: UniProt predicts a signal peptide or a membrane-spanning region. PROTAC: ubiquitination databases record sites on it.
Gene: Protein-coding gene on chromosome 8 (38,386,207 to 38,409,527, forward strand). Ensembl gene ENSG00000165046.
Subcellular location: Mitochondrion inner membrane
Subcellular location (Human Protein Atlas): Nucleoplasm; Cytosol; Nuclear bodies
Gene Ontology:
Molecular function: transmembrane transporter activity; ribosome binding
Biological process: mitochondrial calcium ion transmembrane transport; mitochondrion organization
Cellular component: mitochondrion; mitochondrial inner membrane
Genetic constraint (gnomAD): Loss-of-function variants: 35 observed, 37.26 expected, observed/expected ratio (o/e) 0.94, 90% interval 0.72 to 1.25. The upper end of that interval is the gene's LOEUF score, 1.25, which puts it in group 5 of 6, group 1 being the genes least tolerant of losing a copy. Missense variants: 409 observed, 426.87 expected, observed/expected ratio (o/e) 0.96, 90% interval 0.88 to 1.04. Synonymous variants: 146 observed, 163.37 expected, observed/expected ratio (o/e) 0.89, 90% interval 0.78 to 1.02.
Homologues: Orthologues: chimpanzee LETM2 (99% identical), macaque LETM2 (97% identical), dog LETM2 (86% identical), rabbit LETM2 (82% identical), pig LETM2 (80% identical), mouse Letm2 (77% identical), rat Letm2 (76% identical), zebrafish letm2 (51% identical), tropical clawed frog letm2 (51% identical). Paralogues in human: LETM1 (44% identical), LETMD1 (15% identical).
Diseases named in the same sentence as LETM2 in open-access papers:
LETM2 is named in the same sentence as 12 diseases in open-access papers, as found by Europe PMC text mining. Sharing a sentence is not in itself a finding about the gene and the disease. The quoted sentences say what the papers report.
esophageal squamous cell carcinoma (2 papers, 2022 to 2024). Esophageal squamous cell carcinoma (ESCC) is a type of esophageal carcinoma (EC) that can affect any part of the esophagus, but is usually located in the upper or middle third. "A study of structural variations in esophageal squamous cell carcinoma (ESCC) found that chromothripsis leads to high-level amplification of FGFR1, LETM2 and NSD3 on chromosome 8." (PMID 38256018, 2024).
gastric cancer (2 papers, 2024 to 2025). A primary or metastatic malignant neoplasm involving the stomach. "It was also reported that overexpression of LETM2 impacts mitochondrial function, linking it to the advancement of gastric cancer." (PMID 40282424, 2025). "Through in-depth analysis of The Cancer Genome Atlas (TCGA) database, our study revealed that in gastric cancer tissues, the expression of LETM2 was significantly increased compared with that in normal tissues adjacent to the cancer." (PMID 38654380, 2024). "Considering the impact of LETM2 on cell cycle progression in gastric cancer, we conducted Western Blot experiments to evaluate the expression of G0/G1 phase-associated cyclins, CDK2, CDK4, CDK6, CyclinB1, and CyclinE2." (PMID 38654380, 2024). "LETM2 expression was significantly increased in gastric cancer tissues compared to normal tissues adjacent to the cancer." (PMID 38654380, 2024). "Furthermore, we observed that in gastric cancer patients, the low-expression group of LETM2 showed a more optimistic prognosis compared to the high-expression group." (PMID 38654380, 2024). "The proliferative ability of gastric cancer cells was inhibited after knocking down the cell lines simultaneously.These in vivo findings further support the inhibitory role of LETM2 in GC cell proliferation." (PMID 38654380, 2024).
lung adenocarcinoma (2 papers, 2011 to 2021). A carcinoma that arises from the lung and is characterized by the presence of malignant glandular epithelial cells. "Using SNP array analysis, we found that a region of chromosome segment 8p11-12 containing three genes–WHSC1L1, LETM2, and FGFR1–is amplified in 3% of lung adenocarcinomas and 21% of squamous cell lung carcinomas." (PMID 21666749, 2011). "The heatmap reveals that HNRNPLL|53258|AT, CA5B|98313|ES, MEGF6|315|ES, and CDKN2A|86000|AP may have positive effects on lung adenocarcinoma while BEST3|23330|AT, TTC39C|44852|AP, AP2B1|40327|AD, LETM2|83399|AT, and MKL1|62348|AP can have adverse effects." (PMID 35004299, 2021).
pancreatic cancer (2 papers, 2022 to 2025). "Pan-cancer survival analysis ground on the TCGA database was implemented to evaluate the predictive value and clinical significance of LETM2, which represented that elevated expression of LETM2 was most significantly associated with dismal prognosis of pancreatic cancer, either poor OS or DFS." (PMID 36230646, 2022). "SLC55A2 (LETM2) promotes tumor growth and metastasis in pancreatic cancer via the PI3K-AKT pathway, with limited evidence in other cancer types." (PMID 40282424, 2025). "Subsequently, immunohistochemical analyses showed that the obviously elevated expression of LETM2 was correlated with abysmal outcomes of pancreatic cancer patients." (PMID 36230646, 2022). "This is the first report on the functional role and molecular mechanism of the newly protein-coding gene, LETM2, in pancreatic cancer." (PMID 36230646, 2022). "Therefore, we hereafter focused on the expression level and prognostic values of LETM2 in pancreatic cancer." (PMID 36230646, 2022). "In conclusion, the study enhanced our understanding of the LETM2-regulated PI3K-Akt signaling axis served as a prognostic and therapeutic target of pancreatic cancer." (PMID 36230646, 2022). "LETM2 may facilitate tumor progression by activating the PI3K-Akt signaling pathway, which provides potential targets for the diagnosis, treatment, and prognosis of pancreatic cancer." (PMID 36230646, 2022).
breast carcinoma (1 paper, 2020). "Evaluation of the median mRNA expression of genes of the amplicon in TCGA breast cancer study discloses that a few genes (GOT1L1, ADRB3, STAR and LETM2) have a very low or no expression in breast cancers." (PMID 32987805, 2020).
pancreatic ductal adenocarcinoma (1 paper, 2022). An infiltrating adenocarcinoma that arises from the epithelial cells of the pancreas. "This study aimed to illustrate LETM2 as the crucial oncogene for tumor progression in pancreatic ductal adenocarcinoma (PDAC)." (PMID 36230646, 2022).
tumor (5 papers, 2011 to 2025). "We demonstrated that LETM2 promotes tumor progression by activating the mTOR pathway, thereby inducing mitochondrial homeostasis and facilitating glycolysis, ultimately leading to accelerated proliferation of GC cells." (PMID 38654380, 2024). "Overexpression of LETM2 (leucine zipper and EF-hand containing transmembrane protein 2) significantly enhanced tumor proliferation and metastasis." (PMID 38654380, 2024). "To better understand the effect of LETM2 on the proliferation ability of GC cells in a complex in vivo environment, we established a nude mice subcutaneous xenograft tumor model." (PMID 38654380, 2024). "In in vitro and in vivo experiments, LETM2 knockdown significantly inhibited tumor proliferation and metastasis, while LETM2 overexpression exerted the opposite effects." (PMID 36230646, 2022). "The results showed that the LETM2 protein expression was remarkably increased in PDAC tumor tissues." (PMID 36230646, 2022). "LETM2 may promote tumor progression by maintaining mitochondrial health and activating glycolysis, offering potential targets for diagnosis, treatment, and prognosis of GC." (PMID 38654380, 2024). "Then, we suggested that LETM2 may facilitate tumor progression by activating downstream PI3K-Akt signaling pathway in PDAC." (PMID 36230646, 2022). "Moreover, we demonstrated that the knockdown of LETM2 significantly promoted cancer cell apoptosis and inhibited tumor migration and proliferation in both in vivo and in vitro experiments." (PMID 36230646, 2022). "Furthermore, IHC staining of the nude mice tissues also verified that the Ki67 was downregulated in the LETM2 downregulation group and it was also reversed in the tumor tissues with the PI3k-Akt pathway activator stimulation." (PMID 36230646, 2022). "Moreover, we demonstrated that LETM2 knockdown significantly inhibited tumor proliferation and metastasis, and promoted cell apoptosis, while LETM2 overexpression exerted the opposite effects." (PMID 36230646, 2022). "Additionally, the tumorigenicity of PDAC cells was decreased by the knockdown of the LETM2 in vivo xenograft tumor model of nude mice." (PMID 36230646, 2022). "However, although there is differential expression of LETM2 in multiple cancers, research on the function and mechanism of LETM2 in tumor development and progression is rare." (PMID 36230646, 2022). "In conclusion, the study proposed that LETM2 may facilitate tumor development by promoting the PI3K-Akt signaling pathway in PDAC, which provides prospective targets for the diagnosis, treatment, and prognosis of PDAC." (PMID 36230646, 2022). "Thus, this study aimed to illustrate LETM2 as the crucial oncogene for tumor progression in PDAC." (PMID 36230646, 2022). "Therefore, we used PI3K inhibitor GDC-0941 and AKT activator SC-79 to conduct rescue experiments in vitro as well as in vivo, in which we noticed that the PI3K-Akt pathway activator can abolish or decrease the effect of inhibiting tumor progression after LETM2 knockdown." (PMID 36230646, 2022). "To clarify the prognostic significance of LETM2 in PDAC patients, we first examined the LETM2 protein expression in six paired samples of PDAC tumor and non-tumor (paracarcinoma) tissues." (PMID 36230646, 2022). "To determine the cellular requirement for genes in the region targeted by the amplification, we assessed the requirement of WHSC1L1, LETM2 and FGFR1 expression for tumor maintenance by depleting them individually using shRNA." (PMID 21666749, 2011). "Specifically, three primary tumor samples with amplified FGFR1 and LETM2 genes had amplicon breakpoints within WHSC1L1, explaining the exclusion of WHSC1L1 from the GISTIC amplification peak." (PMID 21666749, 2011).
tumor (continued). "Furthermore, IHC staining in specimens of 60 PDAC patients enrolled in our study verified that LETM2 expression was significantly elevated in tumor tissue in comparison with the matched non-tumor tissue." (PMID 36230646, 2022). "LETM2 knockdown could not only suppress PDAC cell proliferation, migration, and invasion, but also promote PDAC cell apoptosis in vitro, while LETM2 overexpression may speed up tumor development and progression." (PMID 36230646, 2022).
cancer (4 papers, 2022 to 2025). A tumor composed of atypical neoplastic, often pleomorphic cells that invade other tissues. "In the current research, we firstly identified LETM2 as an oncogenic hallmark of PDAC by pan-cancer analysis of the TCGA + GTEx database and the results of GEPIA analysis also supported this finding." (PMID 36230646, 2022). "Then, we observed differential expression of LETM2 in different malignancies in the TCGA-GTEx pan-cancer dataset, which was most significantly associated with a dismal prognosis of PDAC." (PMID 36230646, 2022). "LETM1 is associated with poor prognosis in various malignant tumors, whereas the biological role and mechanism of action of LETM2 in cancer remain poorly understood." (PMID 38654380, 2024). "In this study, we analyzed the expression level and prognostic value of LETM2 in multiple cancers using pan-cancer analysis." (PMID 36230646, 2022). "The analyses based on the TCGA-GTEx dataset indicated that the LETM2 expression was obviously elevated in several cancers, and it was the most significantly related to the dismal prognosis of PDAC." (PMID 36230646, 2022). "We analyzed the expression level and prognostic value of LETM2 in multiple cancers using pan-cancer analysis and found that the LETM2 expression was the most significantly related to the dismal prognosis of PDAC." (PMID 36230646, 2022). "To summarize, we observed differential expression of LETM2 in various malignancies in the pan-cancer analysis, which was most prominently correlated with the dismal prognosis of PDAC." (PMID 36230646, 2022). "We explored the clinical value and molecular mechanism of LETM2 in GC progression, which may serve as a potential therapeutic target in cancer management." (PMID 38654380, 2024). "However, studies involving the biological roles and functional mechanisms of LETM2 in malignant tumors are scarce." (PMID 36230646, 2022). "Moreover, pan-cancer survival analysis on the ground of the TCGA database was implemented to evaluate the predictive value and clinical significance of LETM2." (PMID 36230646, 2022).
LETM2 also shares sentences with these, for which no sentence is quoted: Pan (1 paper); schizophrenia (1); squamous cell lung carcinoma (1); Wolf-Hirschhorn syndrome (1).